SCD5 (stearoyl-CoA desaturase 5)
Description:
Stearoyl-CoA desaturase that utilizes O(2) and electrons from reduced cytochrome b5 to introduce the first double bond into saturated fatty acyl-CoA substrates. Catalyzes the insertion of a cis double bond at the delta-9 position into fatty acyl-CoA substrates including palmitoyl-CoA and stearoyl-CoA. Gives rise to a mixture of 16:1 and 18:1 unsaturated fatty acids. Involved in neuronal cell proliferation and differentiation through down-regulation of EGFR/AKT/MAPK and Wnt signaling pathways.
Synonyms: ACOD4; SCD2; SCD4; FLJ21032; FADS4; HSCD5; DFNA79
Tractability: Small molecule: a high-quality ligand is known; it belongs to a druggable protein family. Antibody: UniProt predicts a signal peptide or a membrane-spanning region. PROTAC: ubiquitination databases record sites on it; a small molecule that binds it is known.
Target class: Enzyme; Oxidoreductase
Gene: Protein-coding gene on chromosome 4 (82,629,539 to 82,798,796, reverse strand). Ensembl gene ENSG00000145284.
Subcellular location: Endoplasmic reticulum membrane
Pathways (Reactome):
Developmental Biology: EGR2 and SOX10-mediated initiation of Schwann cell myelination
Gene expression (Transcription): MLL4 and MLL3 complexes regulate expression of PPARG target genes in adipogenesis and hepatic steatosis
Metabolism: Fatty acyl-CoA biosynthesis
Gene Ontology:
Molecular function: oxidoreductase activity; palmitoyl-CoA 9-desaturase activity; stearoyl-CoA 9-desaturase activity; iron ion binding; acyl-CoA desaturase activity; oxidoreductase activity, acting on paired donors, with oxidation of a pair of donors resulting in the reduction of molecular oxygen to two molecules of water
Biological process: unsaturated fatty acid biosynthetic process; fatty acid biosynthetic process; lipid metabolic process
Cellular component: endoplasmic reticulum membrane
Genetic constraint (gnomAD): Loss-of-function variants: 20 observed, 32.03 expected, observed/expected ratio (o/e) 0.62, 90% interval 0.44 to 0.91. The upper end of that interval is the gene's LOEUF score, 0.91, which puts it in group 3 of 6, group 1 being the genes least tolerant of losing a copy. Missense variants: 381 observed, 465.38 expected, observed/expected ratio (o/e) 0.82, 90% interval 0.75 to 0.89. Synonymous variants: 173 observed, 184.78 expected, observed/expected ratio (o/e) 0.94, 90% interval 0.83 to 1.06.
Homologues: Orthologues: chimpanzee SCD5 (99% identical), macaque SCD5 (98% identical), pig SCD5 (90% identical), rabbit SCD5 (89% identical), dog SCD5 (87% identical), guinea pig SCD5 (82% identical), Drosophila melanogaster Desat1 (48% identical), Drosophila melanogaster Desat2 (48% identical), Drosophila melanogaster CG8630 (46% identical), Caenorhabditis elegans fat-6 (43% identical), Caenorhabditis elegans fat-7 (42% identical), Drosophila melanogaster Fad2 (42% identical), and 1 more. Paralogues in human: SCD (58% identical).
Diseases named in the same sentence as SCD5 in open-access papers:
SCD5 is named in the same sentence as 88 diseases in open-access papers, as found by Europe PMC text mining. Sharing a sentence is not in itself a finding about the gene and the disease. The quoted sentences say what the papers report.
breast carcinoma (19 papers, 2015 to 2025). "Analysis of breast cancer samples showed that low expression of SCD5 was associated with more aggressive cancer phenotypes, and correlates with the prognosis of breast cancer." (PMID 36980176, 2023). "It was downregulated in breast cancer, and low expression of SCD5 was associated with more aggressive breast cancer phenotypes, such as high histological grade, late stage, and HER2 overexpression." (PMID 37373069, 2023). "A recent analysis of breast cancer samples showed that low SCD5 expression was associated with more aggressive cancer phenotypes and shorter patient survival." (PMID 36980176, 2023). "Upregulated SCD5 expression was found to be associated with longer relapse free survival (RFS) in breast cancer (HR = 0.74, 95% CI 0.67–0.82, p = 1.3e−08)." (PMID 33903614, 2021). "Analysis of samples from public databases showed that SCD5 expression was down-regulated in some human cancers including breast cancer, and low expression of SCD5 was associated with more aggressive breast cancer phenotypes." (PMID 33903614, 2021). "Taken together, SCD5 expression signatures could be associated with response of neoadjuvant chemotherapy in breast cancer." (PMID 33903614, 2021). "Thus, we speculated that high SCD5 expression characteristic was associated with unfavorable response to chemotherapy in breast cancer." (PMID 33903614, 2021). "SCD5 is an integral membrane protein involved in lipid metabolism in the endoplasmic reticulum, and its presence can optimize the prognosis of breast cancer and improve the responsiveness to neoadjuvant chemotherapy." (PMID 39119088, 2024). "It was shown, in a metastatic cell model for breast cancer, that over-expression of SCD5 decreased extracellular matrix deposition and hampered metastatic spreading." (PMID 36980176, 2023). "Another study on nude mice injected with SCD5-overexpressing A375M melanoma cells and 4T1 mammary carcinoma cells showed significantly less metastasis formation in the lung compared to the mice injected with control cells." (PMID 37373069, 2023). "A recent study in > 4900 breast cancer patients reports that relatively higher expression of SCD5 improves relapse-free survival." (PMID 36581893, 2022). "In this article, we have already found that the SCD5 expression in triple-negative breast cancer was higher than that in other breast cancer subtypes using public datasets." (PMID 33903614, 2021). "Taken together, these findings indicated that down-regulated SCD5 expression was related to more aggressive breast cancer phenotypes, such as high histological grade, late stage and HER2 overexpression." (PMID 33903614, 2021). "The results revealed that SCD5 mRNA expression was under-expressed in high histological grade and late-stage breast cancer." (PMID 33903614, 2021). "In GEO data, upregulated SCD5 mRNA expression was observed in TNBC compared to other breast cancer subtypes (log2[Fold change] > 0.5, p < 0.05)." (PMID 33903614, 2021). "Different from the role of SCD1 in human cancers, our data revealed that SCD5 had differential expression profiles in human cancers, and in breast cancer, SCD5 was upregulated in normal tissue compared to tumor." (PMID 33903614, 2021). "Tumor samples from TCGA and GEO databases were used to explore the distribution of SCD5 mRNA expression in different breast cancer molecular subtypes." (PMID 33903614, 2021). "In order to explore the roles of SCD5 in breast cancer, multiple analyses were performed on the Human Protein Atlas, TCGA and GEO databases." (PMID 33903614, 2021). "We then performed microarray datasets downloaded from GEO (GSE20194, GSE20271 and GSE25055) to further define the value of SCD5 in curative effect assessment of anthracycline/taxane-based NACT for breast cancer." (PMID 33903614, 2021). "We also investigated the effect of SCD1 and SCD5 expression on prognosis in breast cancer by using Kaplan–Meier plotter dataset." (PMID 33903614, 2021).
breast carcinoma (continued). "We further explored the correlation between the gene expression and survival in breast cancer to better understand the clinical significance of SCD5." (PMID 33903614, 2021). "This significant difference was confirmed by the expression analysis of SCD5 in primary breast cancer samples and normal breast samples derived from TCGA data (n = 1284) (p = 3.691e−7)." (PMID 33903614, 2021). "Downregulated SCD5 expression was related to more aggressive breast cancer phenotypes, such as high histological grade, late stage and HER2 overexpression." (PMID 33903614, 2021). "SCD5 is also known to play an important role in oncogenesis in breast cancer, and the expression of this enzyme increases in anaplastic thyroid carcinoma." (PMID 32392704, 2020). "The role of SCD5 in promoting mammary cancer cell survival is consistent with the incomplete response to neoadjuvant chemotherapy observed in breast cancer patients presenting significantly higher levels of the enzyme." (PMID 29849946, 2018). "The aim of the present study was to gain further insight into the mechanisms responsible for the SCD1-mediated regulation of breast cancer cell migration, as well as the assessment of the possible role played by SCD5 in this setting." (PMID 29849946, 2018). "According to SCD5 antimetastatic function, its restoration reduces the capability to disseminate of both the A375M human melanoma and 4T1 murine mammary carcinoma cell lines evaluated in in vivo models." (PMID 29484133, 2018). "Our previous studies showed the antimetastatic role of the desaturating enzyme SCD5 in both human melanoma and murine mammary carcinoma cells." (PMID 29484133, 2018). "The observed increase in SCD5 levels induced by CAFs outlines a further role of these stromal cells in breast cancer progression by the promotion of tumor cell survival." (PMID 29849946, 2018). "SCD5-driven reprogramming of FA metabolism has been shown to block epithelial–mesenchymal transition, thereby reducing the probability of metastatic events and tumor malignancy in breast cancer and melanoma." (PMID 37047490, 2023). "Furthermore, SCD5 has also been demonstrated to be a promising predictive biomarker for response to neoadjuvant chemotherapy in breast cancer, and a reliable prognostic factor for metastatic uveal melanoma." (PMID 37047490, 2023). "Taken together, SCD5 might serve as a tumor suppression gene and negatively regulate cancer cell growth and proliferation in breast cancer." (PMID 33903614, 2021). "In addition, we also analyzed the mRNA expression of SCD5 in breast cancer patients with different molecular and clinicopathological characteristics." (PMID 33903614, 2021). "In summary, our study was the first to investigate the roles of SCD5 in breast cancer." (PMID 33903614, 2021). "Stated thus, these data suggested that SCD5 might serve as a regulator of diverse signaling networks to suppress cell proliferation and migration in breast cancer." (PMID 33903614, 2021). "The results showed that SCD5 might serve as a tumor suppressor gene during breast cancer progression." (PMID 33903614, 2021). "Survival analysis revealed that SCD5 expression was related to prognosis in breast cancer." (PMID 33903614, 2021). "Taken together, SCD5 was involved in the development and progression of breast cancer and might be a predictive biomarker for response to NACT." (PMID 33903614, 2021). "Although a compensatory effect was observed in some breast cancer models, SCD5 is not able to restore the effects of SCD1 deficiency." (PMID 31936134, 2020). "Increasing expression of SCD5 promoted tumor cell survival in breast cancer." (PMID 32190687, 2020). "It has also been observed that SCD1 inhibitors abrogate the protective effects of SCD1 on palmitate-induced lipoapoptotic cell death of β-pancreatic cells Furthermore, different studies in breast cancer models have demonstrated an upregulation of SCD5 in human cancer cells." (PMID 31936134, 2020).
breast carcinoma (continued). "SCD5 may also have an oncogenic effect in other cancers, as shown on a breast cancer model, where it increased the viability of cancer cells." (PMID 32392704, 2020). "However, SCD5 knockdown caused the necrosis of MCF-7 cells, suggesting the involvement of CAF-induced SCD5 expression in the maintenance of breast cancer cell survival." (PMID 31284458, 2019). "Thus, in contrast to the observation in mouse cells, it is unlikely that inhibition of SCD1 would activate the alternative pathway by upregulation of SCD5 in human cancer cells, at least in the breast cancer model." (PMID 31284458, 2019). "Our findings suggest that elevated expression levels of FASN1, SCD1, SCD5, and CKα may closely correlated with enhanced levels of saturated and monounsaturated lipids in breast cancer cell lines." (PMID 26061164, 2015). "Interestingly, a study showed that depletion of SCD5 in MCF-7 breast cancer cells induced necrosis." (PMID 37373069, 2023). "However, the expression of SCD5 was lower in more aggressive metastatic breast cancer and melanoma cells than primary breast cells and low-invasive melanoma, and supplementation with OA reduced A375M melanoma cell malignancy by reducing the dissemination capability, impairing tumor spread." (PMID 37373069, 2023). "Furthermore, SCD5 might help distinguish breast cancer patients, especially TNBC patients, who are likely to benefit from neoadjuvant chemotherapy." (PMID 33903614, 2021). "Moreover, our data also suggested that SCD5 could be a potential predictor of response to anthracycline/taxane-based neoadjuvant chemotherapy in patients with breast cancer, especially in TNBC patients." (PMID 33903614, 2021). "SCD5 may play an important role through the PPAR pathway in breast cancer chemotherapy." (PMID 33029112, 2020). "However, an experiment on murine neuroblastoma Neuro2a cells showed that SCD5 exhibited substrate specificity only for palmitic acid but not for stearic acid, in contrast to observations in A375 melanoma and 4T1 breast cancer cells, where SCD5 did desaturate stearic acid." (PMID 32392704, 2020). "The authors hypothesized a predicting role for the peroxisome proliferator-activated receptor (PPAR), a transcription factor which is involved in tumor growth and whose activation leads to SCD5 gene expression, in affecting the response to taxane-based chemotherapy in breast cancer." (PMID 29849946, 2018). "The analysis showed that the ratio SCD5/SCD1 was significantly upregulated in low histological grade and early-stage breast cancer compared to high histological grade and late-stage breast cancer." (PMID 33903614, 2021). "Then, we further explored the relationship between SCD5 expression and HER2/ERBB2 expression by using Oncomine (Gluck breast cancer) and GEO (GSE20194) datasets." (PMID 33903614, 2021). "Therefore, the role of SCD5 in breast cancer remains unclear." (PMID 33903614, 2021). "Here, we further explored the mechanisms involved in the SCD1-based modulation of breast cancer cell migration and investigated the role of the other human SCD isoform, SCD5." (PMID 29849946, 2018). "Moreover, in both melanoma and high-grade breast cancer cells, we demonstrated that reducing SPARC secretion, either through oleic acid administration or forced production of SCD5, has beneficial effects on antitumor immunity." (PMID 40890836, 2025). "The results of GO analysis showed that the 608 SCD5-related DEGs (up-regulated in breast cancer with high SCD5 expression) were involved in negative regulation of cell cycle (the most significant biological process)." (PMID 33903614, 2021). "In conclusion, SCD5 could serve as a predictive biomarker of pathological response to NACT and play a carcinostatic role in breast cancer." (PMID 33903614, 2021). "Based on functional enrichment analysis, the most affected biological functions in high SCD5-expressing breast cancer tissues were involved in negative regulation of cell cycle." (PMID 33903614, 2021).
breast carcinoma (continued). "Neither SCD1 nor SCD5 was found to be significantly related to OS in breast cancer by using Kaplan–Meier plotter dataset (not shown in this paper)." (PMID 33903614, 2021). "Here, this study was performed to comprehensively analyze SCD5 expression characteristics, prognostic value and correlation with pathological response to NACT for better understanding the clinical significance of SCD5 in breast cancer." (PMID 33903614, 2021). "However, we found that the ratio SCD5/SCD1 was significantly different in different histological grades and pathological stages of breast cancer." (PMID 33903614, 2021). "Furthermore, as mentioned in Section 6, the co-culture of MCF-7 and MDA-MB-231 breast cancer cells with CAFs induced the expression of SCD1 in both cancer cell lines, and the overproduction of SCD5 isoform in MCF-7 cells." (PMID 31284458, 2019). "Unlike SCD1, the second human isoform of SCD, SCD5, seemed not to play a major role in the migratory ability of highly invasive breast cancer cells since its knockdown did not produce relevant variations in MDA-MB-231 cell migration." (PMID 29849946, 2018). "In the present study, we deepened our previous findings by focusing more in detail on the mechanisms involved in the SCD1-based control of breast cancer cell migration and demonstrated an unpredicted role for the other human SCD isoform, SCD5, in the maintenance of tumor cell survival." (PMID 29849946, 2018). "Unlike SCD5, we did not observe obvious clinical significance of SCD1 in breast cancer by using public databases." (PMID 33903614, 2021). "Unlike SCD5, we did not observe significant differential SCD1 mRNA expression among different breast cancer histological grades or pathological stages (not shown in this paper)." (PMID 33903614, 2021).